IL6 (interleukin 6)
Diseases named in the same sentence as IL6 in open-access papers (continued):
Sharing a sentence is not in itself a finding about the gene and the disease.
Hypertension (continued). "Patients with CRS mostly have common manifestations such as fever, tachycardia, hypoxia, dyspnea, hypertension, coagulopathy, and elevated serum cytokines, including interleukin-6 (IL-6)." (PMID 34790207, 2021). "In sex-stratified analyses, men with hyperglycaemia had higher BMI and higher total/HDL cholesterol levels while women with hyperglycaemia had higher IL-6 levels, consumed more alcohol, and suffered more frequently from hypertension." (PMID 34206644, 2021). "The treatment of rats in preeclampsia with anti TNF-α antibodies attenuated hypertension and decreased IL-6 and sVCAM-1 levels." (PMID 33663436, 2021). "The levels of pro‐inflammatory factors such as TNF‐α, IL‐1β and IL‐6 increase with the severity of hypertension, and affect its prognosis." (PMID 34331512, 2021). "IL-6 levels in the patient fluctuated from the baseline to 2–4-folds after treatment, but side effects were mild with only grade 1 hypertension and fatigue." (PMID 33589520, 2021). "Compared with healthy cases, monocytes from patients with essential hypertension are preactivated and would produce more IL-6 after stimulation with angiotensin II or lipopolysaccharide." (PMID 34055114, 2021). "Old age, hypertension, higher circulating levels of neutrophils, IL-6, and NLR and lower levels of T lymphocytes, CD4+ lymphocytes, and CD8+ T cells were significantly associated with the risk of developing pneumonia." (PMID 33239109, 2020). "In the present study, baseline hs-CRP and IL-1β levels in the hypertension group were significantly higher than those in the control group (normal BP at both baseline and follow-up), whereas baseline IL-6 levels showed an increasing trend." (PMID 32292598, 2020). "ICV administration of AZD8797, a CX3CR1 inhibitor, attenuates fructose-induced hypertension and expression of pro-inflammatory cytokines IL-1β, IL-6, and TNF-α." (PMID 32532282, 2020). "Prolonged mercury exposure increases the risk of developing hypertension through systemic inflammation, as demonstrated by elevated levels of serum inflammatory cytokines TNF-α, IL-2, IL-6 and anti-inflammatory cytokine IL-10." (PMID 33083327, 2020). "A few studies have also demonstrated a relationship between hypertension and inflammatory biomarkers (e.g. C-reactive protein, D-dimer and interleukin-6), immune activation and microbial translocation." (PMID 32487185, 2020). "The levels of TNF-α, IL-2, IL-6 and IL-10 in serum were determined in mercury-exposed participants, suffering from hypertension." (PMID 33083327, 2020). "In summary, we showed that AZD8797, a CX3CR1 inhibitor, attenuated fructose-induced hypertension and expression of pro-inflammatory cytokines, IL-1β, IL-6, and TNF-α." (PMID 32532282, 2020). "IL-6 contributes to stable hypertension by affecting vascularremodeling and endothelial function.The IL-6/sIL-6R complex is involved in controlling vascularpermeability." (PMID 33659786, 2020). "Thereby, confirming the potential role of IL-6 trans-signaling in inflammation-mediated hypertension." (PMID 32848763, 2020). "In a previous study, KO of IL-6 has been observed to reverse angiotensin II (Ang II)-induced hypertension by down-regulating JAK2-STAT3 phosphorylation." (PMID 33099539, 2020). "The potential role of ADAM17-mediated shedding of IL-6R and its role in IL-6 trans-signaling-mediated inflammation and its impact on hypertension needs investigation." (PMID 32848763, 2020). "Alternatively, Nesami and co-workers found CoQ10 supplementation to be effective in decreasing some pro-inflammatory factors like IL-6 and CRP, in association with increasing adiponectin levels in patients with mild hypertension." (PMID 32375340, 2020). "Multivariable Cox regression analysis showed that blood sodium level > 145 mmol/L, lymphocyte count < 1000 cells/μL, CVD other than hypertension, and higher IL-6 serum levels were independent predictors of in-hospital mortality." (PMID 33257703, 2020).
Hypertension (continued). "Plasma IL-6 concentrations have been measured in both hypertensive patients and an Ang II-induced mouse hypertension model." (PMID 33099539, 2020). "Studies on animals have also confirmed the elevated IL-6 in hypertensive mice receiving Ang-II, and the knockdown of IL-6 attenuated Ang-II-induced hypertension." (PMID 32848763, 2020). "There are data, that IL-6, produced by endothelial cells during hypertension, activates transcriptional factor STAT3 and induces transdifferentiation of the monocytes into CD16+ cells." (PMID 33854919, 2020). "The rise in TNF-α receptor-2 and IL-6 concentration lead to increased level of endothelin leading to high blood pressure." (PMID 33014422, 2020). "In the same way, exercise can ameliorate hypertension in a murine model, with a marked decrease in IL-6 expression, followed by a reduction in microglial activation in the hypothalamus." (PMID 31534953, 2019). "Some of the individual proteins that we investigated in this study have previously been evaluated in relation to incident hypertension, such as interleukin-6 and tumor necrosis factor receptor-2." (PMID 31581667, 2019). "Increased circulating levels of M-CSF and IL-6 during hypertension have been reported in both humans and rodents, consistent with the present PCR study." (PMID 31444374, 2019). "In the present study, WEC significantly reduced the serum levels of CRP, TNF-α, IL-6, and sVCAM-1 in middle-aged and elderly subjects with overweight or prehypertension/mild hypertension." (PMID 31394768, 2019). "The present study provides evidence regarding high levels of IL-6 and MCP-1 and a predisposition to inflammation in patients with young-onset hypertension compared with those in normotensive individuals." (PMID 31655529, 2019). "IL-6 increased vascular smooth muscle cell proliferation, which is a characteristic of the early stages of hypertension." (PMID 31655529, 2019). "These cardiovascular changes were accompanied by reductions in circulating IFN-γ and IL-6 as well as activated (CD38+) and immunosenescent (CD57+CD28null) CD8+T cells, previously implicated in hypertension." (PMID 31504461, 2019). "Ablation of IL-6 in these mice attenuated the angiotensin II-induced hypertension and features of CKD, including proteinuria and renal fibrosis." (PMID 30871285, 2019). "A study conducted on healthy men demonstrated a correlation between increased blood pressure (hypertension) and elevated levels of circulating interleukin (IL)-6." (PMID 31655529, 2019). "The production of cytokines like IL-6, IL-23, and IL-1β can also skew T cells produce IL-17A, which we have previously shown to be involved in hypertension." (PMID 29800237, 2018). "Increased circulating levels of pro-inflammatory cytokines (PICs) including Tumor necrosis factor alpha (TNF-α), Interleukin-6 (IL-6), and Interleukin-1 beta (IL-1β) have been noted in both human hypertension and animal models of hypertension." (PMID 29520237, 2018). "IP-10 was also associated with hypertension, and controls showed a significant correlation between frequency of CD4CD38HLDR+ and levels of IL-6, TNF-α, and IP-10." (PMID 29997625, 2018). "In the present study, we found that the hypertension-elevated renal cortex IL-6 and COX-2 were attenuated after twelve weeks of exercise training." (PMID 29461477, 2018). "Reports have demonstrated that various PICs such as TNF-α, IL-1β, and IL-6 play a vital role in the development of hypertension." (PMID 29573749, 2018). "The role of IL-6 in hypertension development requires additional study in order define the specific contribution of IL-6 in the initiation and maintenance of the hypertensive phenotype." (PMID 29186034, 2017). "IL-6 serum level was higher in patients with NASH and associated hypertension (25.48 versus 36.79, p = 0.014)." (PMID 28852433, 2017). "IL-6 and IL-13 levels significantly decreased in combined hypertension disorders when compared with normal pregnant women." (PMID 28348564, 2017).
Hypertension (continued). "Adventitial Nox2 generated ROS also plays an important role in angiotensin II-hypertension associated IMT by modulating the secretion of monocyte chemoattractant protein-1 (MCP-1) and interleukin 6 (IL-6)." (PMID 29135921, 2017). "Similar to our cohort of RA patients, the increased levels of IL-6 are associated with traditional CVR factors as smoking, overweight and hypertension in apparently healthy women, and in elderly women with previous history of CV events." (PMID 29137196, 2017). "Taken together, these pharmacological and genetic data provide the first insights into downstream mechanisms of IL-6 signaling in angiotensin II-induced hypertension." (PMID 29186034, 2017). "TNF-α and IL-6 levels were associated with hypertension in all models (TNF-α: P<0.001; IL-6: model 1, P = 0.002; model 2, P = 0.029; model 3, P = 0.044)." (PMID 28837559, 2017). "More recently, our laboratory found a direct correlation with plasma IL-6 levels and hypertension produced by angiotensin II infusion over a wide range of doses as well as with plasma angiotensin II levels." (PMID 29186034, 2017). "Since this initial observation, several other studies provide additional support for increased IL-6 expression in hypertensive patients as well as several experimental models of hypertension." (PMID 29186034, 2017). "The goal of this review is to highlight the effects of the proinflammatory cytokine IL-6 on oxidative and inflammatory mechanisms in general, in hypertension, and in response to angiotensin II." (PMID 29186034, 2017). "AT1R inhibition has proven to reduce inflammation in hypertension, as well as LPS-induced inflammation, via the reduction of IL-1β, IL-6 and TNFα levels." (PMID 28416734, 2017). "Genetic inhibition of IL6 resulted in reduction of cardiac inflammation and fibrosis in an Ang II high-salt-induced hypertension mouse model." (PMID 28707261, 2017). "A study conducted with essential hypertension patients showed that the interleukin-6 (IL-6) level was significantly reduced in the forest pre-post intervention group (p < 0.05) but not in urban control group." (PMID 29165173, 2017). "The study showed that the level of IL-6 in patients with high blood pressure was higher while the level of NO was lower." (PMID 28042549, 2017). "T cell-produced cytokines (such as tumor necrosis factor alpha, or TNFα) and many of the interleukins (such as IL-6) have been shown to play a role in hypertension." (PMID 27092251, 2016). "Deletion of IL-6 inhibited cardiac inflammation, fibrosis and dysfunction in an angiotensin II and high salt induced hypertension model of mice." (PMID 26972749, 2016). "Angiotensin-converting enzyme 2 (ACE2) overexpression in the PVN has also been shown to attenuate both ANG II-induced hypertension and expression of the pro-inflammatory cytokines TNFα, IL-1β, and IL-6 in the PVN43." (PMID 27092251, 2016). "Recently, it has become evident that the immune system and inflammatory markers such as Interleukin-6, Tumor necrosis factor alpha and C-reactive protein are also essential in the pathogenesis of hypertension." (PMID 26989902, 2016). "IL-6 stimulates the synthesis of C-reactive protein and also promotes VSMC proliferation, a hallmark of hypertension and atherosclerosis." (PMID 26989902, 2016). "Thus, it seems that IL-6 may be considered as a risk factor for hypertension and CAD." (PMID 28033321, 2016). "The cytokines TNF-α, IL-6 and IL-17 can themselves produce hypertension when infused into pregnant rats." (PMID 26569331, 2015).
Hypertension (continued). "AngII induced renal inflammation and hypertension is mediated by interleukin 6 (IL-6), and characterized by increased expression of tumor necrosis factor (TNF)-α, and monocyte chemoattractant protein-1 (MCP-1)." (PMID 26121471, 2015). "This study also examined the associations of IL-6 and TNF-α with anthropometric measurement and the effect of co-morbidity with hypertension using rural and urban dwellers in the Ashanti region, Ghana." (PMID 26391589, 2015). "IL-6 is an important cytokine in angiotensin II-induced hypertension, where the magnitude of BP increase is significantly reduced in IL-6 KO mice." (PMID 25505598, 2014). "We also found that prenatal LPS (0.79 mg/kg) exposure up-regulates IL-6 and TNF-a mRNA expression in fetus and causes hypertension in offspring rats." (PMID 24498431, 2014). "It has been demonstrated that monocyte count is a better independent risk factor of CVD than several conventional risk factors such as C-reactive protein (CRP), inflammatory cytokine interleukin-6 (IL-6), fibrinogen, hypertension, and cigarette smoking." (PMID 24398220, 2014). "In conclusion, we found that in obese patients with T2D the development of hypertension depends on the increases in IR and pro-inflammatory cytokines, especially IL-6 levels." (PMID 24686488, 2014). "Hypertension is considered to cause elevation of inflammatory cytokines such as tumor necrosis factor-alpha (TNF-α), interleukin-6(IL-6)." (PMID 25474403, 2014). "Bautista reviewed multiple studies and reported a positive association between hypertension and some proinflammatory markers including C-reactive protein (CRP), interleukin-6 (IL-6), and tumor necrosis factor alpha (TNF-α)." (PMID 23691280, 2013). "Angiotensin II (Ang II) stimulates the release of IL-6, and a previous report demonstrates that Ang II hypertension is attenuated in IL-6 knockout mice." (PMID 22848208, 2012). "The results clearly demonstrated time-dependent progression of hypertension and heart dysfunction as evidenced by gradually increased left ventricular mass index, NT-proBNP, IL-6 as well as gradually decreased cardiac function as assessed by echocardiography." (PMID 22935137, 2012). "In current study we determined multiple biomarkers including NT-proBNP, IL-6 and adiponectin at multiple time points during transition period from hypertension to heart dysfunction." (PMID 22935137, 2012). "Cardiovascular risk factors, such as smoking and hypertension don't correlate with PBMC telomerase activity, in agreement with previously published data, but strongly affect IL-6 in the present study." (PMID 22558213, 2012). "The current study demonstrates that PPAR-α is necessary for the attenuation of plasma IL-6, an anti-inflammatory property that reduces blood pressure during Ang II-induced hypertension." (PMID 22848208, 2012). "The current study suggests that the activation of PPAR-α reduces mean arterial pressure during chronic Ang II-hypertension through an anti-inflammatory process that involves the significant reduction of plasma IL-6." (PMID 22848208, 2012). "Nevertheless, it was substantial enough to indicate an important correlation between high blood pressure and IL-6 (CC-genotype), which should be examined on a larger study sample." (PMID 19804633, 2009). "Although this indicates an important correlation between high blood pressure and IL-6 genotype, larger studies are needed to confirm this significance." (PMID 19804633, 2009). "Further, IL-6 induces an increase in plasma angiotensinogen and angiotensin II, leading to development of hypertension." (PMID 18416854, 2008). "Conventional risk factors were more frequent among patients with IL-10 concentrations above median, including elevation of CRP and IL-6 but excluding previous MI and hypertension." (PMID 17690160, 2008). "Furthermore, in a model of Ang II-induced arterial hypertension in C57BL/6 mice, increased BP was associated with elevated plasma IL-6 levels." (PMID 41592077, 2026).
Hypertension (continued). "IL-6 may contribute to the initiation, progression, and maintenance of hypertension by reducing nitric oxide bioavailability, increasing vascular oxidative stress, regulating angiotensin II expression, and altering vascular function and structure." (PMID 40005478, 2025). "In parallel, IL‐6 and C reactive protein plasma levels were associated with BPV in hypertensive patients, suggesting systemic inflammation as a pathophysiological mechanism contributing to TOD in hypertension." (PMID 40454610, 2025). "The dietary approaches to stop hypertension score (DASH-S) demonstrated a significant positive association with adiponectin and an inverse association with CRP in early pregnancy and other proinflammatory biomarkers (TNF-α and IL-6)." (PMID 40043850, 2025). "However, the role of targeting inflammation in hypertension treatment, particularly through modulation of inflammatory markers like interleukin-6 (IL-6), remains less understood." (PMID 39760129, 2025). "CRP is a marker of systemic inflammation, often elevated in hypertension, and may contribute to vascular dysfunction, with elevated levels of both IL-6 and CRP found in patients with dilated left atria." (PMID 40005478, 2025). "IL-6 and TNF-a are inflammatory markers linked directly and indirectly to both hypertension and AF." (PMID 40005478, 2025). "Both TNF-α and IL-6 have been shown to directly contribute to the development of hypertension." (PMID 39484785, 2025). "Notably, interleukin-6 and urinary isoprostanes were significantly associated with MACE in adults with preclinical hypertension (systolic 120–129 mmHg and diastolic < 80 mmHg)." (PMID 41286084, 2025). "In multivariate logistic regression, independent predictors of APE were: age (OR 1.06, 95% CI 1.02–1.10, p = 0.004), hypertension (OR 2.94, 95% CI 1.24–6.97, p = 0.014), NT-proBNP (OR 1.0003 per pg/mL, 95% CI 1.0001–1.0006, p = 0.008), and IL-6 (OR 1.012 per pg/mL, 95% CI 1.002–1.022, p = 0.019)." (PMID 41303223, 2025). "The expression of miR-92a-3p, miR-423-5p, and miR-320a-3p in T lymphocytes of Kazakh hypertensive patients is downregulated, leading to increased expression of inflammatory factors such as IL-17 and IFN-γ, the elevation of IL-6, and the occurrence of hypertension." (PMID 41366965, 2025). "Compared with the control group TNF-α (1.11 ± 0.42); Compared with IL-6 (1.1 ± 0.49), TNF in lymphocytes of hypertensive patients-α (1.42 ± 0.72); The expression of IL-6 (1.48 ± 0.68) gene showed an increasing trend in the hypertensive patient group, with no statistical significance (P > .05)." (PMID 41366965, 2025). "Take together, hypertension could exacerbate the increase in IL-6 protein expression in the PFC of mice as early as 2 w into Pb exposure compared with that in the hippocampus or hypothalamus." (PMID 39853035, 2025). "Moreover, the IL-6 protein expression in the PFC of mice in the Pb + hypertension group heighted at 2 w exposure and reached to fourfold that of control group at 12 w exposure." (PMID 39853035, 2025). "Importantly, interleukin-6 and urinary isoprostanes were significantly associated with MACE among adults with preclinical hypertension, alongside traditional risk factors such as age, male sex, current smoking, and LDL." (PMID 41286084, 2025). "It has been reported that in these patients, high levels of immunoglobulin E stimulate mast cells to release IL-6, while neutrophils produce greater amounts of superoxide anions, contributing to vascular damage and, consequently, to the pathophysiology of hypertension." (PMID 41155215, 2025). "Moreover, a meta-analysis revealed that chromium reduces the levels of inflammatory biomarkers such as IL-6 and TNF-α, which are major risk factors for hypertension and cardiovascular disease." (PMID 38730326, 2024).